ACE (angiotensin I converting enzyme)
Diseases named in the same sentence as ACE in open-access papers (continued):
Sharing a sentence is not in itself a finding about the gene and the disease.
diabetic nephropathy (continued). "Overactivation of the renin-angiotensin-aldosterone system (RAAS) has been implicated in the development and progression of diabetic nephropathy, and ARB/ACE inhibitor blockade is currently the mainstay of treatment." (PMID 36818747, 2023). "Apoptosis pathways have previously been implicated as one of the pathophysiological mechanisms in the development of diabetic nephropathy and can be attenuated by ACE or ARBII inhibition." (PMID 38054547, 2023). "In people who are hypertensive and have microalbuminuria, however, there is relatively strong evidence to suggest that ACE inhibition slows progression of diabetic nephropathy in people with type 1 diabetes and microalbuminuria." (PMID 34979961, 2022). "The authors concluded that ACE inhibitors and ARBs are equally effective in slowing the progression of diabetic nephropathy." (PMID 35484505, 2022). "For over two decades, the standard treatment of diabetic nephropathy has focused on strict glycemic control and blood pressure control with angiotensin-converting enzyme (ACE) inhibitors or angiotensin receptor blockers (ARBs)." (PMID 34909290, 2021). "Consistent with a protective action of endogenous kinins and B2R activation in diabetic nephropathy, the beneficial effect of ACE inhibition is suppressed by a B2R antagonist in mice or rats." (PMID 33800422, 2021). "We sought to evaluate the miRNA status in the diabetic nephropathy and to assess the physiological relevance with respect to ACE inhibition in diabetic mice." (PMID 32085655, 2020). "The renoprotective effects beyond BP control of RAS blockers including ARBs and ACE inhibitors have been well established in CKD patients (particularly the patients with diabetic nephropathy)." (PMID 29453374, 2018). "The effect of the mineralocorticoid antagonist finerenone was also discussed, and a recent clinical trial in diabetic kidney disease found reduced albuminuria in patients treated with a combination of ACE inhibitors or ARBs and finerenone." (PMID 27190345, 2017). "Consistent with these animal experiments, studies in human diabetic nephropathy showed that the ACE inhibitor, perindopril was able to reduce TGF-ß mRNA in a sequential renal biopsy study and the ARB, losartan, was shown to lower urinary TGF-ß excretion." (PMID 26741142, 2016). "We also compared the degree of renal protection afforded by luseogliflozin with that seen in rats treated with an ACE inhibitor, which is the standard of care in diabetic nephropathy." (PMID 26169541, 2015). "The following genes had significant association with diabetic nephropathy: eNOS, AT2R, SUMO4, IL-10, VEGF, MTHFR, ACE, and VDR." (PMID 26587547, 2015). "Other studies have indicated that the ACE gene is a factor that contributes to the manifestation of GD, diabetic nephropathy and Ob." (PMID 25879409, 2015). "In humans with DKD, it has been demonstrated that RAS blockade (both ACE inhibitors and angiotensin II receptor blockers) slows down the progression of diabetic nephropathy." (PMID 26239552, 2015). "Blockade of RAS by angiotensin converting enzyme (ACE) inhibitors is an effective strategy in treating diabetic kidney diseases." (PMID 24330074, 2014). "Three way interaction of Asian, male and ACE D allele on all-cause CKD, diabetic nephropathy and non-diabetic nephropathy." (PMID 24498151, 2014). "The ACE genes have been assessed in relation to HT and diabetic nephropathy for many years, but the results of these studies are conflicting." (PMID 24562335, 2014). "Angiotensin-converting enzyme (ACE) inhibitors and angiotensin receptor blockers (ARBs), both commonly used in preventing diabetic nephropathy, act on this pathophysiology." (PMID 25298884, 2014). "The aim of our study was to find out the role of ACE ID and PPARG P12A polymorphisms in genetic susceptibility of diabetic nephropathy in south Indian population." (PMID 24282791, 2013).
diabetic nephropathy (continued). "In summary, we conducted a prospective, open-label trial of ACTH gel in 14 patients with ACE inhibitor-resistant nephrotic syndrome secondary to advanced diabetic nephropathy." (PMID 24159603, 2013). "A number of well-controlled studies have shown that ACE inhibitors are capable of reducing proteinuria and of stabilizing renal function in diabetic and non-diabetic nephropathy." (PMID 23446441, 2013). "Carnosine has been reported to protect against renal injury, along with having antioxidant activity, inhibition of AGE formation, and ACE inhibition property, suggesting that CNDP1 contributes to conferring susceptibility to diabetic nephropathy." (PMID 23342076, 2013). "For patients with type 2 diabetes treatment with an ACE inhibitor to prevent the occurrence or progression of diabetic kidney disease is highly cost-effective." (PMID 22022539, 2011). "In (incipient) diabetic nephropathy, ACE inhibitors and angiotensin II receptor type I blockers (ARBs) also exert their renoprotective effects." (PMID 20441574, 2010). "Although the ID genotype is generally the most frequent type of ACE genotype, the plausibility of ID genotype as a potential predictor for diabetic nephropathy is highly unlikely." (PMID 21031056, 2010). "A beneficial effect of ACE inhibitor on diabetic kidney disease has been observed in clinical trials, which underscores the importance of ACE in diabetic CRI." (PMID 20353610, 2010). "All potential risk factors for diabetic nephropathy including age, ethnicity, blood pressure, HDL, triglyceride, gender, ACE genotype and HbA1Cwere assessed by stepwise logistic regression procedure." (PMID 21031056, 2010). "While ACE inhibitors are clinically used in the treatment of diabetic nephropathy, they might also help suppress the transition from AKI to CKD by inhibiting Ang II production." (PMID 40332817, 2025). "The peripheral RAS plays an important role in the regulation of blood pressure and fluid volume, and AT1 receptor blockers (angiotensin receptor blockers; ARBs) and ACE inhibitors (ACEIs) are clinically used to treat or prevent hypertension, diabetic nephropathy and chronic heart failure." (PMID 38200077, 2024). "Interestingly, the use of angiotensin-converting enzyme (ACE) inhibitor (e.g., enalapril) in experimental models of diabetic nephropathy demonstrates a temporary improvement in albuminuria." (PMID 38673935, 2024). "Additionally, studies have shown that MRAs effectively reduce mortality and hospitalization in HF patients with diabetic kidney disease when combined with ACE inhibitors or ARBs." (PMID 39541086, 2024). "However, it was noticed that ACE activity in the group of patients with diabetic nephropathy and the A/A genotype was significantly lower compared to the control group." (PMID 38398308, 2024). "However, statistically lower ACE activity was observed in the group of patients with diabetic nephropathy and the A/A genotype compared to the control group with the same genotype (p = 0.004)." (PMID 38398308, 2024). "The aim of this study was to assess the frequency of two selected ACE polymorphisms (rs4343 and rs4646994) in patients with diabetic nephropathy, both with and without kidney transplantation." (PMID 38398308, 2024). "The D allele of the ACE insertion/deletion (I/D) gene variant, which is associated with higher ACE activity, could be related to increased risk of DPN as well as diabetic nephropathy in Caucasian39,40." (PMID 38200077, 2024). "Low ACE activity in patients with diabetic nephropathy may result from compensatory adaptation aimed at reducing the production of additional angiotensin II (Ang II)." (PMID 38398308, 2024). "Currently, management of diabetic nephropathy is based on blood pressure control by angiotensin receptor blocker (ARB)/angiotensin-converting enzyme (ACE) inhibitors, lipid-lowering by statins, precise glycemic control, weight loss, salt restriction, and smoking cessation." (PMID 36818747, 2023).
diabetic nephropathy (continued). "Renin-angiotensin-aldosterone system plays important roles in the development of diabetic nephropathy (DN), and angiotensin converting enzyme (ACE) is the key factor in the process from angiotensin I to angiotensin II, but the variation and roles of serum ACE in DN patients are still unclear." (PMID 36992775, 2022). "An increased risk of AKI may occur in individuals who have chronic diseases of the kidney, particularly those suffering from diabetic nephropathy, due to an already present increased regulation of enzyme ACE and reduced regulation of ACE-2." (PMID 36237801, 2022). "In summary, our results imply that elevated serum ACE levels in DN patients may be an indicator for diabetic nephropathy, and continuously increased ACE is a possible signal of diabetic nephropathy progression." (PMID 36992775, 2022). "db/db UNx-ReninAAV mice display key features of advanced diabetic kidney disease, including extreme albuminuria and severe glomerulosclerosis, which can be ameliorated by current clinical standard of care using ACE inhibitor (lisinopril) and SGLT2i (empagliflozin) combination therapy." (PMID 35884965, 2022). "Similar observations have been made in experimental diabetic nephropathy, although the role of kinins in the effect of ACE inhibitors may be greatest at the early stage of the disease." (PMID 33800422, 2021). "Furthermore, diabetic nephropathy is often treated with ACE inhibitor as well as lipid lowering treatment and aspirin." (PMID 27872861, 2016). "Second, apart from the differences in calcium channel blockers and diuretics, ACE inhibitors and ARBs might elicit different effects on diabetic nephropathy." (PMID 25918454, 2015). "However, recently conducted meta-analysis showed consistent association between ACE D allele or DD genotype and ESRD risk in diabetic nephropathy patients." (PMID 25587546, 2014). "Evidence from both animal and clinical studies supports the hypothesis that blockade of RAS by ACE inhibitors (ACEIs) and angiotensin receptor blockers (ARBs) is an effective strategy in treating diabetic kidney diseases." (PMID 24330074, 2014). "They suggested that these findings may have implications for the management of diabetic nephropathy using ACE inhibitors especially among type 2 diabetic Asians." (PMID 25587546, 2014). "The vascular genes ACE (Angiotensin-converting enzyme), and PPARG (peroxisome proliferator activated receptor gamma) are involved in alterations in vascular endothelium, and are suggested to play a role in the susceptibility of diabetic nephropathy." (PMID 24282791, 2013). "Hence, additional studies considering gene-gene and gene-environment interactions should be investigated to estimate the overall risk of the ACE and PPARG genes in the pathogenesis of diabetic nephropathy." (PMID 24282791, 2013). "Similarly, as expected theoretically, combination of selective ETA receptor blocker and ACE inhibitor has produced impressive benefit, including regression of lesions in model of diabetic nephropathy." (PMID 22235363, 2011). "Since all P values were greater than 0.05, it demonstrates null association between the ACE alleles and diabetic nephropathy, irrespective of severity of nephropathy." (PMID 21031056, 2010). "Our study revealed a highly significant difference in the presence of DD genotype and D allele of ACE gene among ESRD patients and normal controls validating that the ACE gene polymorphism is an important genetic determinant of non-diabetic nephropathies too." (PMID 17042963, 2006). "Clinical practice guidelines recommend prescribing angiotensin converting enzyme (ACE) inhibitors and angiotensin receptor blockers (ARBs) which are the two major classes of renin–angiotensin aldosterone system inhibitors (RAASi) to prevent and manage diabetic nephropathy at any stage." (PMID 35484505, 2022).
diabetic nephropathy (continued). "The possibility to have ACE-independent Ang II generation launched a series of studies evoking a possible role of chymase-dependent Ang II formation in various human tissues, such as the vasculature, heart and kidneys after a high salt intake and in patients with diabetic nephropathy." (PMID 33396702, 2020). "In our investigations, we reviewed five studies which investigated the association between eNOS, ACE, MTHFR, and factor V Leiden and the interaction between them and diabetic nephropathy and reach a coherent result while GWAS could be helpful and reduce time and other expenses." (PMID 26587547, 2015). "Angiotensin-I converting enzyme (ACE) is one of the key enzymes in the renin-angiotensin-aldosterone system (RAAS) and the insertion (I)/deletion (D) polymorphism of this gene has been studied extensively with renal and cardiovascular complications of diabetic nephropathy." (PMID 25587546, 2014). "Some studies have shown that different polymorphisms in angiotensin 1-converting enzyme (ACE) gene are associated with development of both persistent microalbuminuria and diabetic nephropathy; however, other recently published reports have not replicated these findings." (PMID 24562335, 2014). "There were significant differences in the genotypes of ACE I/D (ID/II, adjusted OR, 1.89; 95% CI, 1.31–2.71) and G2350A (GA/GG, adjusted OR, 1.65; 95% CI, 1.14–2.40; AA/GG, and adjusted OR, 2.04; 95% CI, 1.28–3.28) between patients with diabetic nephropathy and controls." (PMID 24977181, 2014). "It is possible that these cases reflect a response to ACE inhibitor/ARB/MRA overdosing or up-titration, especially given the expected presence of renal artery stenosis or diabetic nephropathy in this cohort." (PMID 39678250, 2024). "Diabetic nephropathy (a CKD) is characterized by decrease in ACE2, increased ACE and Ang-II-mediated tubular and glomerular damage as a result of renal RAS activation." (PMID 32901433, 2021). "Hyperkalemia is one of the major reasons for guideline-recommended ACE inhibitors and ARBs are discontinued or fail to reach guideline-recommended dosing for CKD and/or diabetic nephropathy patients." (PMID 31910208, 2020). "For patients with diabetic nephropathy, a significant reduction in BP has been achieved with the administration of an MR blocker as an add-on therapy to an ARB or ACE inhibitor." (PMID 31239535, 2019). "Taken together, studies had suggested that upregulated ACE expression and downregulated ACE2 expression were seen at both the glomerular and tubular levels in established diabetic nephropathy." (PMID 29582239, 2018). "With the standard therapy of angiotensin-converting enzyme (ACE) inhibitors or angiotensin II receptor blockers (ARB), combined with glucose, lipid, and blood pressure control, the outcome for patients with diabetic nephropathy remains poor." (PMID 24744808, 2014). "It is well known that angiotensin-converting enzyme (ACE) and angiotensin II receptor are involved in the pathogenesis of arteriosclerosis, diabetic nephropathy and other ectopic fibrosis diseases." (PMID 25360706, 2014). "Since then, it has been reported that both angiotensin converting enzyme (ACE) inhibitors and angiotensin II receptor blockers (ARBs) delay the development and progression of diabetic nephropathy." (PMID 24284398, 2013). "Existing evidence indicates that it is reasonable for continued use of ACE inhibitor plus ARB combination for proteinuric nephropathies and resistant hypertension, and for diabetic nephropathy." (PMID 23866091, 2013). "Studies using models of type 2 diabetes have shown at early stages, prior to diabetic nephropathy developing, that ACE2 expression is reduced in the kidney, while ACE expression is elevated." (PMID 22121476, 2012). "Our data suggest that common variants in the AGTR1, ACE, and MTHFR genes are not strongly associated with diabetic nephropathy in our patients with type 1 diabetes." (PMID 39446857, 2024).
diabetic nephropathy (continued). "We do not think that patient age, ACE inhibitor use, comorbidities (excluding diabetic nephropathy), male gender, and ASA score (excluding ASA IV) directly or indirectly affect AKI development." (PMID 39268493, 2024). "Renin-angiotensin system (RAS) inhibitors, such as angiotensin-converting enzyme (ACE) inhibitors or angiotensin II receptor blockers (ARBs), are recommended as first-line drugs for hypertensive patients with diabetic nephropathy mainly for their blood pressure (BP)-lowering effects." (PMID 36100672, 2023). "Despite tremendous efforts and ongoing research, until recently there was no specific therapy for diabetic nephropathy (DN) or other chronic progressive kidney diseases (CKD) besides angiotensin-converting enzyme (ACE) inhibition." (PMID 36171965, 2022). "Therefore, angiotensin-converting enzyme (ACE) inhibitors and angiotensin type 1 (AT1) receptor blockers are widely used in diabetic nephropathy at present, which partly interfere with TGF-β expression mediated by ANG II." (PMID 34327204, 2021). "Some studies demonstrated that blockade of RAS with either Angiotensin-Converting Enzyme Inhibitors (ACE-Is) or angiotensin receptor blockers (ARBs) slows down (but does not completely stop) the progression of diabetic nephropathy." (PMID 29914534, 2018). "Some studies have shown that many target proteins, such as angiotensin-converting enzyme (ACE), protein kinase C (PKC), and α-glucosidase, might be a therapeutic target for diabetic nephropathy." (PMID 29853965, 2018). "The discovery of an intrarenal RAS (iRAS) has been crucial to understanding the renoprotective effect of ACE inhibitors (ACEi) and Ang II receptor blockers (ARB) in non neoplastic kidney diseases with fibrotic and proliferative characteristics such as diabetic nephropathy." (PMID 28809959, 2017). "Despite their common use as first-line therapy for selected patients with chronic hypertension and for the prevention of diabetic nephropathy, ACE inhibitors are not indicated for women during pregnancy and lactation due to their excretion into breast milk." (PMID 25926796, 2015). "However, the preventative and therapeutic effect of combined ACE inhibition and ARB therapy on diabetic nephropathy is still insufficient to maintain kidney function." (PMID 25298884, 2014). "Odds ratio of ACE I/D and all-cause CKD, diabetic nephropathy, non-diabetic nephropathy using assumption of allele type, genotype, dominant and recessive model." (PMID 24498151, 2014). "In conclusion, the ACE and PPARG genes do not play a key role in conferring risk for diabetic nephropathy." (PMID 24282791, 2013). "In conclusion, the ACE and PPARG genes do not have a key role in conferring risk for diabetic nephropathy." (PMID 24282791, 2013). "Treatment with the ACE inhibitor imidapril partially prevented diabetic nephropathy; these investigators did not study the effect of an ARB." (PMID 24215514, 2013). "Angiotensin converting enzyme (ACE) inhibitors slow down the progression of diabetic nephropathy independent of an elevated blood pressure." (PMID 22022539, 2011). "We did not observe any gender-dependent association between the ACE I/D gene polymorphism and T2DM or diabetic nephropathy." (PMID 21031056, 2010). "We conclude that in this study the role of ACE I/D gene polymorphism susceptibility to both T2DM and/or diabetic nephropathy was not demonstrated." (PMID 21031056, 2010). "Interestingly, antihypertensives, such as angiotensin converting enzyme (ACE) inhibitors and angiotensin receptor blockers, reduce AGE accumulation in concert with the severity of diabetic nephropathy." (PMID 18840258, 2008). "Nevertheless, this minor effect is reversible, and as with angiotensin-converting-enzyme inhibitors (ACE-i) and angiotensin-receptor blockers (ARBs), it provides renal protection on the long-run with an attenuation of the accelerated decline in GFR, characteristic of diabetic nephropathy." (PMID 32787602, 2020).